STK3 (serine/threonine kinase 3)
Diseases named in the same sentence as STK3 in open-access papers (continued):
Sharing a sentence is not in itself a finding about the gene and the disease.
tumor (continued). "A previous study has found that the deletion of STK3 in mouse liver results in tissue overgrowth and tumor development, demonstrating its importance in suppressing carcinogenesis." (PMID 29270239, 2017). "Additional integrated in silico analysis provided evidence that rs7827435 affects STK3 expression, which in turn is significantly correlated with tumor aggressiveness and patient prognosis." (PMID 25707771, 2015). "After a comprehensive consideration combining the druggability evaluation of small molecules and the stability of binding conformation, aminopterin emerged as the prior candidate and demonstrated significant STK3-inhibiting and tumor-suppressing effects in vitro." (PMID 40604818, 2025). "Conversely, overexpression of STK3 impeded tumor progression." (PMID 38436783, 2024). "Our study demonstrated that prolonged and steady ROS stimulation significantly increased the autophosphorylation of STK3, which facilitates its inhibitory function on tumor progression, providing evidence that the phosphorylation level determines the biological activity of STK3." (PMID 38436783, 2024). "STK3/4 kinases are highly conserved components of the Hippo pathway, regulating critical cellular processes such as immune responses, cell differentiation, organ regeneration, and tumor development." (PMID 38436783, 2024). "Amplification of STK3 led to tumor size suppression and cell apoptosis in ESCC, and the deletion of FOXO1 could reverse the effect." (PMID 38436783, 2024). "We then conducted various assays to confirm the tumor suppressor role of STK3 in ESCC." (PMID 38436783, 2024). "However, we and others have recently reported that STK3 has a pro-tumorigenic role in certain cancers that is distinct from its widely accepted role as a tumor suppressor." (PMID 37345153, 2023). "As a tumor suppressor in normal tissues such as the heart, our studies suggest that we may take advantage of STK3 inhibition to prime normal cells for protection against anthracycline chemotherapy." (PMID 37345153, 2023). "Furthermore, our research has shown underexpression of genes associated with tumor formation and cancer cell migration, including AKT Serine/Threonine Kinase 3 (AKT3), Serine/Threonine Kinase (ATM) and Pseudopodium Enriched Atypical Kinase 1 (PEAK1) gene." (PMID 38074096, 2023). "However, in our expression analysis with the RNA-seq dataset from TCGA, we found that the expression of STK3 was upregulated in the ESCC tumor tissues, which is inconsistent with our assumptions and needs further analysis." (PMID 29270239, 2017). "Upon deeper analysis of STK3 expression patterns in GC patients, we unveiled a frequent amplification of STK3 and significant correlation with poorer clinical outcomes, suggesting that this widely recognized tumor suppressor gene may exhibit oncogenic properties in GC progression." (PMID 40604818, 2025). "However, it is thought that CD8+ T-cell expression in OSA is suppressed by invading tumour cells; therefore, further work needs to investigate whether elevated STK3 expression has the capability to mediate immune cell infiltration in this cancer type." (PMID 40566602, 2025). "Moreover, STK4 and STK3 have been established as tumour suppressor proteins." (PMID 32555725, 2020). "Deeper investigations into commonly overexpressed genes, including ASPN, STK3 and BAMBI, via immunohistochemistry revealed novel findings on cellular protein expression in canine tumours." (PMID 40566602, 2025). "Both STK3 and STRN3 are two important components of the Hippo pathway, which is a key tumour suppressor pathway involved in tissue regeneration, angiogenesis, tumour suppression and metastasis, immune response, and drug resistance." (PMID 38215077, 2024). "Mechanically, ELFN1-AS1 plays an oncogenic role by binding to the protein kinase domain of thousand and one amino acid protein kinase (TAOK1), a tumor suppressor in GC, and disrupting the TAOK1-STK3 interaction, leading to decreased STK3 phosphorylation." (PMID 39528458, 2024).
tumor (continued). "In particular, the STK3, C9orf78 and STRN3 genes were the direct targets of both miR-34c and miR-449a, and their regulation are predictive of tumour progression." (PMID 38215077, 2024). "STK3/MST2 and STK4/MST1 are critical components of the Hippo pathway, which play a pivotal role in organ size control and tumor suppression." (PMID 33082313, 2020). "To further confirm the requirement of Hippo kinases for RASSF2-mediated tumor suppression we generated mice with conditional gene inactivation of both MST1 (Stk4) and MST2 (Stk3) in hematopoietic cells (Vav1-Cre)." (PMID 32029705, 2020). "In contrast, STK3 deletion led to the decreased activity of the oncogenic YAP1 signaling, which might result from its significant inhibition on the tumor cell malignancy." (PMID 40604818, 2025). "There have been limited studies demonstrating the crucial role of STK3 in negative tumor regulation, and further investigation is needed to determine its function in ESCC." (PMID 38436783, 2024). "While these findings contradict the current signaling dogma that STK3 is a tumor suppressor, it is not an implausible notion." (PMID 37345153, 2023). "RAS bound with RASSF5, activate MST1/235,44 to form STK3/MST2 and STK4/MST1 complexes in the hippo signaling pathway that plays a crucial role in tumor suppression by limiting proliferation and stimulating apoptosis where SAV1, MOB1A/B act as effector molecules." (PMID 32884013, 2020). "We also found a correlation between STK3 and CD8+ T-cells in the tumor microenvironment." (PMID 33062724, 2020). "Due to the deletion of STK3/4, which leads to organ overgrowth and tumor advancement, it is reasonable to speculate about additional non-canonical roles of STK3/4." (PMID 38436783, 2024). "Taken together, these findings create a precedent that STK3 may also have a noncanonical tumor-promoting role in BCa and can be targeted to reduce BCa growth and proliferation." (PMID 37345153, 2023). "STK3 and BAMBI qRT-PCR results validated significant overexpression of the genes in tumour compared to patient-matched, non-tumour tissues (n = seven matched pairs of samples, p ≤ 0.05 for both genes)." (PMID 40566602, 2025).
cancer (45 papers, 2010 to 2025). A tumor composed of atypical neoplastic, often pleomorphic cells that invade other tissues. "STK3 variants, present in 3.2–15% of several cancer types, resulted in impaired kinase and suppressive capabilities within the Hippo signalling pathway." (PMID 40566602, 2025). "Now as STK3 has demonstrated regulatory functions in both DNA repair and cancer stem cell population maintenance, we wondered if the expression level of STK3 can affect the drug sensitivity to chemotherapy." (PMID 40604818, 2025). "STK3 expression dysregulation has also shown to have pro-oncogenic effects in different cancer types." (PMID 40566602, 2025). "More importantly, the co-treatment of 5-FU and STK3-deletion showed superior effectiveness on inhibiting cancer cell proliferation and stemness." (PMID 40604818, 2025). "By further subgrouping the cancer cells, the STK3+ and YAP1+ cells were classified into the same Seurat clusters (cluster 4 and 5)." (PMID 40604818, 2025). "Mechanistically, the activation of STK3 accelerated the cell cycling and DNA repair response of GC cells while contributing to the maintenance of cancer stem cell population as well." (PMID 40604818, 2025). "Meanwhile, STK3 upregulation is vital for cancer stem cell population maintenance and DNA repair progress, and thus contributes to the acquisition of chemo-therapy resistance." (PMID 40604818, 2025). "The STK3-mediated biological processes, such as DNA repair and cancer cell stemness maintenance, are closely correlated with chemotherapy resistance." (PMID 40604818, 2025). "Collectively, these findings enhance our understanding of the multifaceted activities of STK3 in biological processes and highlight its significance in various disease states, particularly cancer." (PMID 38436783, 2024). "In cancer research, Raf-1 and Akt can interact with STK3 kinases to inhibit STK3 dimerization with RASSF1A, thus promoting cell proliferation, transformation, and survival." (PMID 38436783, 2024). "In contrast, SUM52PE cells upon STK3 inhibition show an induction of cell cycle inhibitor p27Kip1 and a decrease in pERK1/2, a fundamental activated pathway for cancer development and progression." (PMID 37345153, 2023). "Serine/threonine kinase 3 (AKT3) is a protein-coding gene that is associated with several cattle immune diseases including different tumors and cancers." (PMID 34677734, 2021). "As an important component of the Hippo pathway, STK3 has been involved in the progression of many types of cancers." (PMID 33062724, 2020). "Because UCN-01 is also inhibiting other kinases, a more specific STK3 inhibitor would be very helpful for mechanistic studies on the role of STK3 in signaling and cancer." (PMID 29876001, 2018). "Obtaining a mechanistic understanding of the differential effect on STK3 depletion in individual AML samples would advance our understanding of the development of selective vulnerabilities in cancer and provide novel opportunities for precision oncology." (PMID 29876001, 2018). "Furthermore, overexpression of β-catenin partially rescued the inhibitory effect of STK3 depletion on the cancer cell stemness acquisition and GC organoid growth." (PMID 40604818, 2025). "Additionally, we observed mutations in genes related to the Wnt pathway, including STK3, UBR5, and BICC1, suggesting their potential role in cancer progression." (PMID 38010945, 2024). "Taking advantage of the druggable divergent roles of STK3 in BCa and normal cells may lead to an increase in overall cancer patient survivorship." (PMID 37345153, 2023). "Beyond BCa, the development of STK3 inhibitors to mitigate the effects of chemotherapy may have a broad impact, such as in childhood cancer survivors who are seven times more likely to die prematurely from cardiac disease than the general population." (PMID 37345153, 2023).
cancer (continued). "Furthermore, it has been shown that STK3 suppresses tumorigenesis through inactivation of the YAP oncogene in several cancer type such as liver cancer and lung cancer." (PMID 29876001, 2018). "However, it is unclear whether STK3 can exert cancer-suppressing effects by regulating the functions of the immune system." (PMID 33062724, 2020). "Meanwhile, Co-upregulation of STK3 and YAP1 was also identified in both all cancer cell lines (R = 0.50) and STAD cell lines only (R = 0.38)." (PMID 40604818, 2025). "In summary, we demonstrated that STK3, against the common knowledge, is transcriptionally regulated by YAP1, and the high expression of STK3 can promote GC progression by manipulating cancer cell malignance." (PMID 40604818, 2025). "Public GC scRNA-seq dataset was adopted, and the results illustrated that STK3 and YAP1 upregulation were largely enriched in the cancer cells within GC TME." (PMID 40604818, 2025). "Reintroduction of STK4 or STK3, into HPV+ cancer cells inhibited their proliferation, migration and invasion." (PMID 32555725, 2020). "hsa-miR-5585-3p_L-3R-1_1ss5AG and hsa-mir-7851-p5_1ss12AC targeting AKT serine/threonine kinase 3 (AKT3) played swinging roles in the tumorigenesis, development, and progression of various types of cancer, including CRC." (PMID 32293320, 2020). "A similar expression pattern of miR-582-5p was observed in liver tumors and contributes to cancer progression by targeting the cyclin-dependent kinase 1 and AKT serine/threonine kinase 3 genes." (PMID 29207642, 2017). "Therefore, the inhibition of STK3/4 is expected to increase YAP1 activity, which can have oncogenic effects in the context of cancer." (PMID 37345153, 2023). "Taken as a whole, these reports reinforce the relevance of a noncanonical role of STK3 in several cancers, including BCa." (PMID 37345153, 2023). "The results strongly supported that the expression of YAP1 and STK3 are significantly and positively correlated, no matter in primary samples or cancer cell lines, in mRNA or protein levels, in bulk scale or single cell scale, and in in-house or public databases." (PMID 40604818, 2025). "This reminds us that STK3 may have another mechanism in inhibiting cancer cell proliferation and migration independent of Hippo." (PMID 38436783, 2024). "Moreover, there are emerging studies that suggest that STK3 and other Hippo kinases have noncanonical roles in certain cancer types." (PMID 37345153, 2023). "Finally, DHHC9's broader oncogenic roles, including immune modulation via PD‐L1 or other substrates (e.g., STK3, DYNLL1), were not explored, leaving gaps in understanding its multifaceted contributions to cancer progression." (PMID 40903842, 2025).
infection (8 papers, 2016 to 2025). The state of being infected such as from the introduction of a foreign agent such as serum, vaccine, antigenic substance or organism. "The results indicated that both the STK3 mRNA level and STK3 protein abundance decreased at an early infection time." (PMID 29226127, 2017). "Further, knock down of MST1/2 by Stk4/Stk3 siRNA in RAW264.7 and THP1 macrophages also led to a significant loss in infection-driven IRF3 activation." (PMID 27883091, 2016).
bacterial infection (2 papers, 2024). "STK3/4 also activates Rac GTPase, promoting the assembly of the TRAF6-ECSIT complex, which is crucial for immune T cells to resist bacterial infections." (PMID 38436783, 2024).
cardiovascular diseases (1 paper, 2023). "Serine/threonine kinases (STK3) is a core component of the Hippo pathway and modulates oxidative stress and inflammatory responses in cardiovascular diseases." (PMID 37056939, 2023).
neurodevelopmental disorder (1 paper, 2021). A behavioral and cognitive disorder with onset during the developmental period that involves impaired or aberrant development of intellectual, motor, or social functions. "Summary of Microtubule associated serine/threonine kinase 3 de novo missense variants identified in neurodevelopmental disorders." (PMID 35095415, 2021).
STK3 also shares sentences with these, for which no sentence is quoted: colorectal cancer (4 papers); retinal detachment (4); adenoma (3); glioma (3); thyroid cancer (3); atherosclerosis (2); cardiac hypertrophy (2); sarcoma (2); schizophrenia (2); adenocarcinoma (1); and epileptic encephalopathy (1); Atrophy (1); autoimmune disease (1); Autoimmunity (1); basal cell carcinoma (1); breast tumors (1); cardiac disease (1); cervical squamous cell carcinoma (1); Chagas disease (1); colonic adenomas (1); dementia (1); E. coli infection (1); fibrosarcoma (1); glioblastoma (1); head and neck cancer (1); head and neck squamous cell carcinoma (1); hypertrophy (1); immune deficiency (1); immune diseases (1); immunodeficiency syndrome (1).
A further 25 diseases each share a sentence with STK3 in 1 paper.